ADO (2-aminoethanethiol dioxygenase)
Description:
Plays a vital role in regulating thiol metabolism and preserving oxygen homeostasis by oxidizing the sulfur of cysteamine and N-terminal cysteine-containing proteins to their corresponding sulfinic acids using O2 as a cosubstrate. Catalyzes the oxidation of cysteamine (2-aminoethanethiol) to hypotaurine. Catalyzes the oxidation of regulators of G protein signaling 4 (RGS4) and 5 (RGS5) and interleukin-32 (IL32).
Synonyms: C10orf22; FLJ14547
Tractability: PROTAC: ubiquitination databases record sites on it; its protein half-life has been measured.
Gene: Protein-coding gene on chromosome 10 (62,804,720 to 62,808,479, forward strand). Ensembl gene ENSG00000181915.
Pathways (Reactome):
Metabolism: Degradation of cysteine and homocysteine
Gene Ontology:
Molecular function: cysteamine dioxygenase activity; iron ion binding; protein binding; oxidoreductase activity, acting on single donors with incorporation of molecular oxygen, incorporation of two atoms of oxygen
Biological process: cellular response to hypoxia; taurine biosynthetic process
Cellular component: mitochondrion; cytosol
Genetic constraint (gnomAD): Loss-of-function variants: 9 observed, 10.57 expected, observed/expected ratio (o/e) 0.85, 90% interval 0.51 to 1.48. The synonymous counts are far from expectation, so gnomAD's model fits this gene poorly and the ratio says little. Missense variants: 355 observed, 318.39 expected, observed/expected ratio (o/e) 1.12, 90% interval 1.02 to 1.22. Synonymous variants: 189 observed, 146.48 expected, observed/expected ratio (o/e) 1.29, 90% interval 1.14 to 1.46.
Homologues: Orthologues: chimpanzee ADO (100% identical), macaque ADO (99% identical), dog ADO (93% identical), pig ADO (92% identical), mouse Ado (84% identical), rat Ado (84% identical), rabbit ADO (78% identical), guinea pig ADO (56% identical), tropical clawed frog ado (52% identical), zebrafish adob (49% identical), zebrafish adoa (48% identical), Drosophila melanogaster CG7550 (23% identical).
Diseases named in the same sentence as ADO in open-access papers:
ADO is named in the same sentence as 26 diseases in open-access papers, as found by Europe PMC text mining. Sharing a sentence is not in itself a finding about the gene and the disease. The quoted sentences say what the papers report.
rheumatoid arthritis (2 papers, 2018 to 2022). A chronic, systemic autoimmune disorder characterized by inflammation in the synovial membranes and articular surfaces. "As this list includes eQTLs such as RNASET2 and ADO, which have not been previously linked to rheumatoid arthritis, this approach might be effective for identifying disease associated eQTL-SNPs." (PMID 29740473, 2018).
uveitis (2 papers, 2021 to 2022). An inflammatory process affecting a part of or the entire uvea. "Genome-wide association studies (GWASs) have provided a powerful tool for the genome-wide analysis of genetic susceptibility to uveitis, revealing several genes associated with uveitis, including IL23R/C1ORF141, STAT4, and ADO/ZNF365/Egr2." (PMID 34869347, 2021).
Alzheimer disease (1 paper, 2015). A progressive, neurodegenerative disease characterized by loss of function and death of nerve cells in several areas of the brain leading to loss of cognitive function such as memory and language. "Our results suggested that AdO exerted the inhibitory effect on neuroinflammation and the promotion effect on microglial phagocytosis, indicating its potential as a nutraceutical or therapeutic agent for neurodegenerative diseases, particularly Alzheimer’s disease (AD)." (PMID 26389923, 2015).
atopic dermatitis (1 paper, 2026). "A chromosome conformation capture study identified the cysteamine dioxygenase (ADO) gene as being associated with atopic dermatitis in differentiating keratinocytes." (PMID 41601200, 2026). "Moreover, atopic dermatitis patients carrying the risk allele (C) exhibited increased levels of ADO in lesional skin." (PMID 41601200, 2026). "RNA sequencing and immunostainings indicated higher ADO expression in lesional skin than in non-lesional skin in atopic dermatitis patients." (PMID 41601200, 2026).
cholangiocarcinoma (1 paper, 2018). A carcinoma that arises from the intrahepatic biliary tree (intrahepatic cholangiocarcinoma) or from the junction, or adjacent to the junction, of the right and left hepatic ducts (hilar cholangiocarcinoma). "Microarray-based expression profiling of 104 resected human cholangiocarcinomas revealed reduced expression of GABRB3, PANK1, and LRRC8A, but not GABRA5 or ADO, compared to micro-dissected bile duct controls." (PMID 29787571, 2018). "Stratifying the cohort of 104 cholangiocarcinomas for RNA expression above and below the mean revealed that low RNA expression of GABRA5, LRRC8a, ADO and PANK1, but not GABRB3, was associated with reduction of the median survival time of patients by 1.8, 2.1, 3.3, and 4.3 years, respectively." (PMID 29787571, 2018).
depression (1 paper, 2015). "At high levels of activity (100Hz), endogenous ADO production in the synaptic cleft can be sufficient to interact with A1R receptors to protect against depression." (PMID 26625935, 2015).
Ewing sarcoma (1 paper, 2018). A small round cell tumor that lacks morphologic, immunohistochemical, and electron microscopic evidence of neuroectodermal differentiation. "The 10q21 variants strongly associated with Ewing's sarcoma are located in a block containing four genes: ADO (encoding cysteamine dioxygenase), ZNF365 (encoding zinc-finger protein 365), EGR2 (encoding early growth response protein 2) and LOC107984012 (unknown function)." (PMID 29719630, 2018).
generalized anxiety disorder (1 paper, 2020). An anxiety disorder characterized by excessive and difficult-to-control worry about a number of life situations. "rs2236295 (ADO) and rs2307441 (POLG) were identified within the first genome-wide association study (GWAS) in Generalized Anxiety Disorder (GAD), and they were characterised as potential predictors of venlafaxine extended release (XR) treatment outcome." (PMID 31941550, 2020).
glioblastoma (1 paper, 2022). The most malignant astrocytic tumor (WHO grade IV). "We detected higher hypotaurine levels but reduced ADO gene expression in IDH1-WT glioblastoma." (PMID 34941573, 2022). "Of note, correlations of ADO gene expression and hypotaurine metabolite levels did not correlate in IDH1-WT glioblastoma." (PMID 34941573, 2022).
glioma (1 paper, 2021). A benign or malignant brain and spinal cord tumor that arises from glial cells (astrocytes, oligodendrocytes, ependymal cells). "ADO expression is significantly higher in GBM when compared to lower grade gliomas and its expression is upregulated in GSCs." (PMID 34588983, 2021). "Moreover, ADO overexpression promotes glioma stemness via NF-κB signalling." (PMID 34588983, 2021).
graft versus host disease (1 paper, 2025). An immune system disorder that occurs after allogeneic hematopoietic stem cell transplant and is a reaction of donor immune cells against host tissues. "In studies on graft-versus-host disease (GVHD), human placental mesenchymal stem cells (hPMSCs) were shown to mitigate GVHD-induced liver injury by reducing the proportion of CD8+PD-1+ T cells via the CD73/ADO/Nrf2 signaling pathway." (PMID 40357368, 2025).
hyperemesis gravidarum (1 paper, 2017). Severe, intractable vomiting during pregnancy (usually the first trimester) accompanied by dehydration, weight loss, and electrolyte imbalances. "A study by Murataet al. proposed that ADO serves to counteract further progression of hyperemesis gravidarum." (PMID 28333936, 2017).
intracranial aneurysms (1 paper, 2021). "To this end, we first studied by immunohistochemical staining ADO expression levels in a tissue microarray containing 108 glioma patient samples ranging from grade 2 to grade 4, and 18 normal control brain sections obtained from intracranial aneurysms and peritumor." (PMID 33483477, 2021).
leprosy (1 paper, 2017). Leprosy is a chronic infectious disease affecting primarily the skin and peripheral nervous system. "The reported peak of association with leprosy per se encompassed the ADO and EGR2 genes." (PMID 28222097, 2017).
osteopetrosis (1 paper, 2020). Osteopetrosis, also known as marble bone disease, is a descriptive term that refers to a group of rare, heritable disorders of the skeleton characterized by increased bone density on radiographs. "The previous investigation indicated that ADO was one of the osteoclast-rich forms of osteopetrosis." (PMID 33304905, 2020).
virus infection (1 paper, 2023). "The molecular characterization, the oxygen-sensing enzyme function, and the role in the virus infection of ADO from mandarin fish (scADO) were explored in the present study." (PMID 37631990, 2023). "Herein, the molecular characterization, the oxygen-sensing enzyme function, and the role in virus infection of ADO from mandarin fish (scADO) were explored." (PMID 37631990, 2023).
tumor (12 papers, 2015 to 2025). "Enzyme CD39 converts extracellular ATP/ADP into AMP, while in the last irreversible step, enzyme CD73 converts AMP into ADO, which binds to A1R, A2AR, A2BR, and A3R receptors on the effector T, NK, tumor cell and tumor associated macrophages (TAMs)." (PMID 34356899, 2021). "It is worth noting that ADO in the tumor environment can bind to A2AR on the DC surface, thereby inhibiting DC maturation and antigen presentation." (PMID 34362890, 2021). "In conclusion, our results demonstrate for the first time that ADO functions in a tumor initiation and progression role in glioma." (PMID 33483477, 2021). "To achieve this, we evaluated the effects of ADO deletion on in vivo tumor growth using an orthotopical mouse xenograft model." (PMID 33483477, 2021). "Unsaturated AdO depolymerized by enzymatic depolymerization exerts anti-tumor, anti-oxidant, and immunomodulatory effects, whereas the saturated AdO prepared by acid hydrolysis posses low bioactivities." (PMID 26389923, 2015). "Accumulation of extracellular ADO in the tumor microenvironment favors cancer progression by activating ADO specific G-coupled protein receptors (GPCRs) expressed on immune cells, endothelial cells, fibroblasts and tumor cells." (PMID 37261423, 2023). "In addition to tumor cells, myeloid-derived suppressor cells (MDSCs), tumor-associated macrophages (TAMs), and regulatory T cells (Tregs) also have the ability to inhibit natural killers by producing molecules such as Il-10, TGF-β, ADO, and IDO." (PMID 39769334, 2024). "In particular, antagonists of A2AR are just occurring to be deployed into oncology, which can block the interaction between ADO and A2AR, thereby alleviating tumor immunosuppression and facilitating the antitumor immune response." (PMID 34362890, 2021). "On the other hand, released SCH prevents the engagement of ADO with A2AR on the surface of various immune cells, which relieves the immunosuppression phenomenon and further enhances DOX-induced tumor-specific cellular immunity." (PMID 34362890, 2021). "Conversely, abrogating the ADO/hypotaurine axis using CRISPR/Cas9-mediated gene editing limited glioblastoma cell proliferation and self-renewal in vitro and tumor growth in vivo in an orthotopical mouse model, indicating that this metabolic pathway is a potential key therapeutic target." (PMID 33483477, 2021). "The engagement of ADO and the ADO 2A receptors (A2AR, an immune checkpoint) on various immune cell surfaces hampers the immune reaction toward tumor cells, further exacerbating tumor immunosuppression." (PMID 34362890, 2021). "Interestingly, human ASNs are Nt-Cys2 proteins and have previously been shown to be implicated in tumour survival, albeit they appear not to be regulated by the human PCO paralogue, 2-AMINOETHANETHIOL DIOXYGENASE (ADO)." (PMID 40439298, 2025).
cancer (7 papers, 2016 to 2025). A tumor composed of atypical neoplastic, often pleomorphic cells that invade other tissues. "RGS4, RGS5 and IL32 are also associated with various cancers, where they contribute to disease proliferation, invasiveness and migration, potentially making ADO a universal drug target for these conditions." (PMID 40404614, 2025). "ADO, itself, has been linked to immune invasion and cancer cell redox homeostasis." (PMID 40404614, 2025). "In the same study, IL-32 protein stability was shown to be regulated by ADO in the RKO cancer colon cell line." (PMID 37313466, 2023). "Moreover, cancer therapies, including PD-1 ICB, upregulated CD73-expression and ADO-AR signaling in the TME, potentially amplifying the role of this IC in patient outcomes." (PMID 37435071, 2023). "Using transcription profiling, we further uncovered that the ADO/hypotaurine axis targets CCL20 secretion through activating the NF-κB pathway to drive the self-renewal and maintenance of glioma ‘cancer stem cells’ or glioma cancer stem-like cells." (PMID 33483477, 2021).
neurodegenerative disease (1 paper, 2015). A disorder of the central nervous system characterized by gradual and progressive loss of neural tissue and neurologic function. "Therefore, the current work proposed that AdO is a potentially therapeutic nutraceutical for treating AD or other neurodegenerative disease." (PMID 26389923, 2015).
ADO also shares sentences with these, for which no sentence is quoted: autoimmune disorders (1 paper); diabetes (1); encephalomyelitis (1); multiple sclerosis (1); Patent ductus arteriosus (1); sarcoma (1); VKH disease (1).